Y_RNA (Y RNA )
Gene: Miscellaneous RNA gene on chromosome 12 (50,939,927 to 50,940,026, reverse strand). Ensembl gene ENSG00000199740.
Homologues: Orthologues: chimpanzee Y_RNA (99% identical), macaque Y_RNA (92% identical), dog Y_RNA (87% identical). Paralogues in human: Y_RNA (87% identical), Y_RNA (86% identical), RNY3 (85% identical), Y_RNA (85% identical), RNY3P1 (84% identical), Y_RNA (84% identical), RNY3P14 (83% identical), Y_RNA (83% identical), RNY3P5 (82% identical), Y_RNA (82% identical), RNY3P7 (81% identical), Y_RNA (81% identical), and 93 more.